SRGN (serglycin)
Diseases named in the same sentence as SRGN in open-access papers (continued):
Sharing a sentence is not in itself a finding about the gene and the disease.
endothelial dysfunction (1 paper, 2015). In vascular diseases, endothelial dysfunction is a systemic pathological state of the endothelium (the inner lining of blood vessels) and can be broadly defined as an imbalance between vasodilating and vasoconstricting substances produced by (or acting on) the endothelium. "Accordingly, the results presented here implicate serglycin in endothelial dysfunction relevant for both diabetic complications and cancer." (PMID 26694746, 2015). "We hypothesized that serglycin is involved in processes relevant for endothelial dysfunction through interactions with partner molecules through its glycosaminoglycan side chains." (PMID 26694746, 2015). "Our aim was to describe the roles of serglycin in processes relevant for endothelial dysfunction." (PMID 26694746, 2015).
enteropathy (1 paper, 2016). "In summary, we show that the SG−/− mice respond by enhanced enteropathy to the T. spiralis infection, suggesting an important role of serglycin proteoglycans in the mounting of mucosal immune responses during infection with T. spiralis." (PMID 27267469, 2016). "In contrast, the SG−/− mice display aggravated enteropathy despite low levels of IL-13 suggesting that other serglycin-dependent mediators overrule the effects of lowered IL-13 levels." (PMID 27267469, 2016). "Hence, serglycin proteoglycans contribute to the control of the enteropathy, possibly through mechanisms mediated via its negatively charged glycosaminoglycan chains, i.e. as a co-factor of inflammatory mediators." (PMID 27267469, 2016). "Twelve days post infection lack of serglycin proteoglycans caused significantly increased enteropathy." (PMID 27267469, 2016). "Interestingly, we found that the lack of serglycin proteoglycans aggravates the enteropathy and cause dysregulated Type 2 cytokine responses at 12 dpi, leading to increased numbers of encysted larvae in skeletal muscle at 5 weeks post infection." (PMID 27267469, 2016).
Giardia infections (1 paper, 2021). "Serglycin-deficient mice have an impaired lipid metabolism and a changed bile and lipid metabolism in the intestine, potentially with associated changes in the intestinal microbiota, can be an important factor in the reduced weight gain during Giardia infections in SG-deficient mice." (PMID 34335577, 2021).
intervertebral disc degeneration (1 paper, 2024). "Our findings indicate that serglycin is a latent biomarker of intervertebral disc degeneration and may contribute to development of diagnostic and therapeutic strategies." (PMID 38167807, 2024). "Taken together, we identify late-stage nucleus pulposus cells and confirm the potential mechanism by which serglycin regulates intervertebral disc degeneration." (PMID 38167807, 2024).
ischemic stroke (1 paper, 2024). A stroke disorder caused by obstruction of blood flow to the brain, due to thrombotic (local blood clot formation) or embolic (due to a blood clot or other material traveling from another site) event. "Taken together, our results revealed the vital role of SRGN in exacerbating microglia-mediated neuroinflammation in ischemic stroke, suggesting the potential of SRGN to be a novel therapeutic target." (PMID 38287411, 2024). "Collectively, we confirmed the upregulation of SRGN after ischemic stroke, which was predominantly originated from microglia." (PMID 38287411, 2024). "In conclusion, we revealed the important role of SRGN in triggering microglial activation and amplifying neuroinflammation after ischemic stroke." (PMID 38287411, 2024). "SRGN acts as a novel therapeutic target in microglia-boosted proinflammatory response following ischemic stroke." (PMID 38287411, 2024). "Up to now, the role of SRGN on microglial activation and ischemic stroke is largely unexplored." (PMID 38287411, 2024). "Especially, the function of SRGN in ischemic stroke and microglia-mediated neuroinflammation is still unknown." (PMID 38287411, 2024). "However, the regulatory function of SRGN in microglia and ischemic stroke was still undetected." (PMID 38287411, 2024).
Klebsiella Infections (1 paper, 2009). Infections with bacteria of the genus KLEBSIELLA. "Notably, mice lacking serglycin were previously shown to be more susceptible to Klebsiella infection than were wild type animals." (PMID 19956711, 2009).
large cell carcinoma (1 paper, 2015). A malignant epithelial neoplasm composed of large, atypical cells. "We also examined the distribution of serglycin in 5 squamous cell carcinomas (moderately and poorly differentiated) and 5 adenocarcinomas (moderately and poorly differentiated), including a large cell carcinoma and a bronchoalveolar carcinoma." (PMID 26581653, 2015).
lymph node metastasis (1 paper, 2021). "Notably, high expression of SRGN was found in 65.8% (25/38) of lymph node metastasis samples, versus 44.7% (17/38) of primary tumors, which suggests that SRGN might be involved in metastasis." (PMID 33456569, 2021).
mesenchymal tumors (1 paper, 2017). "In conclusion, by a combined approach of next generation sequencing and high throughput immunohistochemistry we identified two novel markers for FDC-S, FDCSP and SRGN, and suggested a highly effective and ready-to-use approach for its differential diagnosis with other mesenchymal tumors." (PMID 28145886, 2017). "In our cohorts CXCL13, CD21, CD35, FDCSP and SRGN were the best markers for FDC-sarcoma diagnosis and could discriminate 21/22 FDC sarcomas from other mesenchymal tumors by linear discriminant analysis." (PMID 28145886, 2017).
metastatic cancer (1 paper, 2016). A carcinoma which has spread from the original site of growth to another anatomic site. "Lung is the major site for metastasis in the MMTV-PyMT model and since serglycin has been implicated in aggressive metastatic cancer we first analysed the number of lung metastases in littermate PyMT+ SG+/- and SG-/- mice, respectively." (PMID 27223472, 2016). "Our finding warrants further investigations on the role of serglycin in metastatic cancer growth, with the aim to characterize the serglycin-dependent metastatic pathways and to identify novel drug targets." (PMID 27223472, 2016).
nasopharyngeal tumor (1 paper, 2013). "Similarly, serglycin was inversely correlated with the expression levels of E-cadherin and positively correlated with the expression level of the mesenchymal marker vimentin in primary nasopharyngeal tumor tissues by immunohistochemistry." (PMID 24205138, 2013).
Obesity (1 paper, 2023). Accumulation of substantial excess body fat. "In that study, the expression of three PGs was altered as a result of obesity: serglycin, versican, and asporin." (PMID 37108048, 2023).
oral cancer (1 paper, 2023). "Additionally, Serglycin (SRGN), a gene with apoptotic function was found to be down-regulated in oral cancer patients, and finally, GPX2, a gene responsible for detoxification and antioxidant activity was found to be up-regulated." (PMID 38234400, 2023).
periodontitis (1 paper, 2024). An acute or chronic inflammatory process that affects the tissues that surround and support the teeth. "An online differential expression analysis conducted using OralExplorer revealed several genes that were significantly upregulated in all six periodontitis-related datasets, including IL-1β, SRGN, CXCR1, FGR, ARHGEF2, and PTAFR." (PMID 38491529, 2024). "The analysis revealed simultaneous significant upregulation of IL1β, SRGN, CXCR1, FGR, ARHGEF2, and PTAFR in all six periodontitis-related datasets." (PMID 38491529, 2024). "Similar to the mRNA expression results, enhanced protein expression of IL1β, SRGN, CXCR1, and PTAFR was observed in the periodontitis group." (PMID 38491529, 2024). "Specifically, we observed that IL-1β, SRGN, CXCR1, and PTAFR exhibited significant upregulation at both the RNA transcript and protein translation levels in periodontitis patients compared to healthy periodontal patients." (PMID 38491529, 2024). "Additionally, we conducted immunohistochemical analysis to explore the protein translation of IL1β, SRGN, CXCR1, and PTAFR in patients with periodontitis." (PMID 38491529, 2024).
soft tissue tumors (1 paper, 2017). "The highest specificity was observed for SRGN, CXCL13 and for complement and Fc receptors (CD21, CD35 and CD23): they were negative in all soft tissue tumors used as controls." (PMID 28145886, 2017). "FDCSP was expressed by two soft tissue tumors, one sinonasal haemangiopericytoma (SNHP-1) and one synovial sarcoma (SS-2); SRGN was negative in all." (PMID 28145886, 2017).
spinal diseases (1 paper, 2024). "As most late-stage IVDD-related spinal diseases require surgical treatment, it is meaningful to prevent IVDD at early stages and to seek natural products, drugs, or compounds that can directly or indirectly suppress SRGN expression to alleviate IVDD54." (PMID 38167807, 2024).
teratocarcinoma (1 paper, 2013). A germ cell tumor characterized by the presence of an embryonal carcinoma component and a teratoma component. "Serglycin was first identified in the rat yolk sac carcinoma cell line L2 and in F9 teratocarcinoma cells." (PMID 24205138, 2013).
tumor (68 papers, 2013 to 2025). "Chemotactic mediated bacterial targeting and accumulation within tumor’s has been associated with tumor hypoxic micro- environment, pre- dominant expression of clusterin, serglycin, TGF- β2 etc." (PMID 38090593, 2023). "After hypoxia treatment in HNSCC cell lines, the expression of SRGN was increased by secretion of cancer-associated fibroblasts, which in turn stimulates tumor exacerbation via Wnt/β-catenin axis." (PMID 35096063, 2022). "SRGN encodes a kind of proteoglycan, which can be secreted by the extracellular matrix of tumor cells to create a pro-inflammatory TME and is regarded as a driving factor of aggressive phenotype." (PMID 35432532, 2022). "Over the last few years, an increasing number of studies have shown that upregulation of serglycin in many tumors is associated with aggressive tumor cells properties." (PMID 35494005, 2022). "The tumor-derived astrocytes lead GBM cells to upregulate periostin and serglycin, which mediate the recruitment of M2 tumor-associated macrophages and mast cells, thereby enhancing its progression." (PMID 33804873, 2021). "SRGN is over expressed in tumor cells and associated with tumor cell aggressiveness and poor prognosis in cancers." (PMID 31455417, 2019). "E-cadherin expression remained at a significantly higher level in the SG-/- primary tumour tissue as compared with SG+/- primary tumour tissue, indicating a less invasive phenotype of serglycin-deficient tumour cells." (PMID 27223472, 2016). "Subcutaneous injection of SG-/- and SG+/- primary tumour cells in SG -competent and -deficient mice, respectively, will address if serglycin expression is required in the tumour cells or in the normal cell compartment to support metastasis." (PMID 27223472, 2016). "Inflammation is a potent driver of tumour progression and serglycin is strongly associated with inflammatory immune responses." (PMID 27223472, 2016). "Although E-cadherin expression was higher in the serglycin-deficient primary tumour tissue, indicating reduced invasiveness, serglycin-deficient tumour cells were still detected in the circulation." (PMID 27223472, 2016). "While we did not see any difference in CD31 density, we observed enhanced tumor vascular perfusion and a decreased number of angiogenic islets in serglycin deficient mice, which suggest a less pro-angiogenic environment." (PMID 25978773, 2015). "Serglycin is highly expressed and secreted by tumor cells themselves and its overexpression is associated with tumor cell aggressiveness and poor disease outcome." (PMID 26581653, 2015). "It is likely that serglycin is implicated in the establishment of a flourishing inflammatory tumor microenvironment that drives cancer cell growth and spreading." (PMID 26581653, 2015). "To address how loss of serglycin affects tumor progression we used the well-characterized RIP1-Tag2 mouse model." (PMID 25978773, 2015). "For the first time we show that serglycin-deficiency affects orthotopic primary tumor growth and tumor vascular functionality of late stage carcinomas." (PMID 25978773, 2015). "Serglycin has been implicated in tumor vessel expansion in addition to its effect on tumor cell aggressiveness." (PMID 25978773, 2015). "As we did not see any difference in frequency of apoptotic cells between the genotypes we conclude that the enhanced tumor volume in serglycin deficient mice was due to increased proliferation." (PMID 25978773, 2015). "Loss of serglycin resulted in a lower number of angiogenic islets, an enhanced perfusion of the tumor vasculature and decreased levels of VEGF and HGF, suggesting that the presence of serglycin influences angiogenesis and vascular function." (PMID 25978773, 2015). "The increased vessel function and the decrease in the number of angiogenic islets that we observed suggest a more balanced angiogenic environment in a serglycin deficient tumor environment." (PMID 25978773, 2015).
tumor (continued). "RIP1-Tag2 positive mice that are serglycin deficient (RT2posSGko) develop a larger tumor mass with a better perfused vasculature than wild-type RIP1-Tag2 positive (RT2posSGwt) mice." (PMID 25978773, 2015). "We however have used a model that is completely serglycin deficient that takes into account the contribution of serglycin from the entire tumor environment." (PMID 25978773, 2015). "Additionally, TTF1-negative LUAD cell lines often overexpress SRGN, encoding the proteoglycan serglycin, which promotes PD-L1 expression, proinflammatory cytokine production and increased tumour invasiveness and represents a potential therapeutic target." (PMID 40849356, 2025). "The association of SRGN with these pathways suggests that it may contribute to tumor progression by modulating immune responses, promoting angiogenesis, and enhancing cell survival and proliferation." (PMID 41476965, 2025). "While cancer‐associated fibroblasts (CAFs) and their secreted factor serglycin (SRGN) are implicated in tumour progression, the regulation of SRGN secretion within the hypoxic tumour microenvironment is unknown." (PMID 41410182, 2025). "Serglycin is also upregulated in cancer-associated fibroblasts in hypoxic conditions and its secretion activates Wnt/β-catenin signaling, leading to enhanced cancer cell stemness, chemoresistance, and tumor growth." (PMID 35494005, 2022). "Taken together, these findings suggested that tumor cell surface receptor CD44 plays an important role in responding to tumor microenvironment-associated ligands, including SRGN, to potentiate cancer cell aggressiveness via triggering cytoskeleton remodeling and pro-survival pathway." (PMID 31898491, 2020). "The presence of serglycin is associated with increased invasion and metastasis of tumor cells." (PMID 28445977, 2017). "The different effects of serglycin-deficiency found in the PyMT model and the RipTag2 model may thus reflect differences in the tumour growth conditions between the two models." (PMID 27223472, 2016). "Potentially, other proteoglycans may compensate for the serglycin-deficiency in growth and vascularization of the primary tumours." (PMID 27223472, 2016). "A recent study found enhanced tumor growth and proliferation in serglycin deficient RIP1-Tag2 mice." (PMID 26694746, 2015). "Furthermore, secreted and cell surface associated serglycin is capable of inhibiting the classical and lectin pathways of complement via its chondroitin sulfate (CS) chains, thus protecting tumor cells from complement system attack." (PMID 26581653, 2015). "Tumor neobiotic diameter is more extensive in HCC patients with high SRGN expression than in low-expressed patients." (PMID 40384866, 2025). "SRGN expression was significantly elevated in macrophages within tumor samples compared to normal tissues, indicating its significant involvement in shaping the TME." (PMID 41476965, 2025). "The cellular interactions at the vascular wall pathway highlight SRGN’s potential role in angiogenesis and the formation of new blood vessels, which is essential for tumor expansion and metastasis." (PMID 41476965, 2025). "Cell communication analysis indicated that SRGN was involved in interactions within the tumor microenvironment (TME), particularly in the VEGF signaling network." (PMID 41476965, 2025). "It has been reported in the literature that SRGN is a downstream target gene of HIF‐1α, and abnormal HIF‐1α/SRGN regulation affects tumour progression and metastasis." (PMID 41410182, 2025). "Second, the immune‐deficient mouse model used in the current study has limitations, as it cannot accurately assess the regulatory function of SRGN in the tumour immune microenvironment." (PMID 41410182, 2025). "IHC confirms SRGN protein overexpression in 56.7% HCC specimens compared to 3.1% non-tumor counterparts." (PMID 41476965, 2025).